CD86 (CD86 molecule)
Description:
Costimulatory molecule that belongs to the immunoglobulin superfamily that plays an important role in T-lymphocyte activation. Acts as the primary auxiliary signal augmenting the MHC/TCR signal in naive T-cells by acting as a ligand for the CD28 receptor which is constitutively expressed on the cell surface of T-cells. May play a critical role in the early events of T-cell activation and costimulation of naive T-cells, such as deciding between immunity and anergy that is made by T-cells within 24 hours after activation. Also involved in the regulation of B cells function, plays a role in regulating the level of IgG(1) produced. Upon CD40 engagement, activates NF-kappa-B signaling pathway via phospholipase C and protein kinase C activation (By similarity). Also acts as an inhibitor of T-cell activation by acting as a ligand for CTLA4, a decoy receptor, thereby blocking CD28-mediated T-cell priming. [Isoform 2]: Interferes with the formation of CD86 clusters, and thus acts as a negative regulator of T-cell activation. (Microbial infection) Acts as a receptor for adenovirus subgroup B.
Synonyms: CD28LG2; B7.2; B7-2; B70; BU63; CD86 v6; FUN-1; LAB72
Tractability: Antibody: its Gene Ontology location is reachable by antibodies, with high confidence; UniProt places it where antibodies can reach, with medium confidence; UniProt predicts a signal peptide or a membrane-spanning region; the Human Protein Atlas places it where antibodies can reach. PROTAC: UniProt records ubiquitination sites on it. Other modalities: an approved drug acts on it.
Target class: Surface antigen
Gene: Protein-coding gene on chromosome 3 (122,055,362 to 122,121,139, forward strand). Ensembl gene ENSG00000114013.
Subcellular location: Cell membrane
Subcellular location (Human Protein Atlas): Plasma membrane; Centriolar satellite
Pathways (Reactome):
Immune System: CD28 dependent PI3K/Akt signaling; CD28 dependent Vav1 pathway; Co-inhibition by CTLA4; Co-stimulation by CD28; Interleukin-10 signaling
Signal Transduction: PI5P, PP2A and IER3 Regulate PI3K/AKT Signaling; PIP3 activates AKT signaling
Disease: Constitutive Signaling by Aberrant PI3K in Cancer
Gene Ontology:
Molecular function: protein binding; receptor ligand activity; coreceptor activity; signaling receptor activity
Biological process: positive regulation of T cell receptor signaling pathway; T cell activation; B cell activation; cell surface receptor signaling pathway; cellular response to lipopolysaccharide; immune response; negative regulation of T cell proliferation; positive regulation of cell population proliferation; positive regulation of DNA-templated transcription; positive regulation of immunoglobulin production; positive regulation of interleukin-2 production; positive regulation of interleukin-4 production; positive regulation of lymphotoxin A production; positive regulation of non-canonical NF-kappaB signal transduction; positive regulation of T cell proliferation; positive regulation of T-helper 2 cell differentiation; T cell costimulation; lymphocyte activation; positive regulation of immune response; positive regulation of signal transduction; signal transduction
Cellular component: cell surface; extracellular exosome; plasma membrane; external side of plasma membrane
Genetic constraint (gnomAD): Loss-of-function variants: 7 observed, 23.67 expected, observed/expected ratio (o/e) 0.3, 90% interval 0.17 to 0.56. The upper end of that interval is the gene's LOEUF score, 0.56, which puts it in group 2 of 6, group 1 being the genes least tolerant of losing a copy. Missense variants: 295 observed, 352.09 expected, observed/expected ratio (o/e) 0.84, 90% interval 0.76 to 0.92. Synonymous variants: 113 observed, 121.07 expected, observed/expected ratio (o/e) 0.93, 90% interval 0.8 to 1.09.
Homologues: Orthologues: chimpanzee CD86 (99% identical), macaque CD86 (94% identical), pig CD86 (60% identical), dog CD86 (57% identical), rabbit CD86 (56% identical), guinea pig CD86 (55% identical), mouse Cd86 (46% identical), rat Cd86 (44% identical). Paralogues in human: CD80 (20% identical), CD274 (16% identical), PDCD1LG2 (13% identical), RNF135 (9% identical), RFPL3 (6% identical), RFPL1 (6% identical), RFPL2 (6% identical), RFPL4A (6% identical), RFPL4AL1 (6% identical), RFPL4B (4% identical), RNF152 (4% identical), SPRYD4 (3% identical).
Diseases named in the same sentence as CD86 in open-access papers:
CD86 is named in the same sentence as 420 diseases in open-access papers, as found by Europe PMC text mining. Sharing a sentence is not in itself a finding about the gene and the disease. The quoted sentences say what the papers report.
melanoma (102 papers, 1998 to 2026). A malignant, usually aggressive tumor composed of atypical, neoplastic melanocytes. "In this study, DCs derived either from in vitro differentiated monocytes or ex vivo from melanoma-draining SLN were transduced with CD80/CD86-targeted fiber-modified Ad5/3 encoding full-length MART-1." (PMID 30022005, 2018). "In melanoma, we identified an 8-gene signature (CD28, CD80, CD86, CTLA4, FAS, IFNG, IL10, and IL12A) associated with survival." (PMID 42216340, 2026). "This was substantiated by immunostaining for TUNEL, CD4, CD8, CD3, CD206, and CD86 in a melanoma syngeneic tumour model." (PMID 41044178, 2025). "Significant increase in the percentage of CD11c+ dendritic cells (DCs) expressing MHC II and the costimulatory CD86 molecule in the spleen of the B16F1 melanoma bearing mice after treatment with A. vulgaris extract have been noticed." (PMID 38920557, 2024). "Material and Methods: Hematoxylin and eosin staining and immunohistochemical staining for CD80, CD86, and PD-L1 were evaluated for clinical data, survival, prognosis, tumor location, malignant melanoma subtypes, tumor size, and prognostic findings." (PMID 37614091, 2024). "Accordingly, elevated CD80 and CD86 levels were observed in macrophages co‐cultured with irradiated melanoma cells." (PMID 38286661, 2024). "When CD86 expression was examined, it was significantly higher in superficial spreading melanoma and lentigo maligna melanoma than in other subtypes." (PMID 37614091, 2024). "As a result, CD80 and CD86 immunohistochemical markers predict the prognosis of malignant melanoma cases." (PMID 37614091, 2024). "Histologic subtype analysis revealed that CD80 and CD86 expression was significantly higher in superficial spreading melanoma and lentigo maligna melanoma." (PMID 37614091, 2024). "By contrast, with the melanoma cells in h-CLATw/M, RD was shown to upregulate the expression of CD86 and IL-12 much more than it did in h-CLAT, suggesting that RD is a tyrosinase- and melanocyte-specific sensitizer." (PMID 36671815, 2023). "CD86 is expressed on the cell membrane of melanoma and activates the T cells, which enhances the anti-tumor effect." (PMID 37716991, 2023). "Accordingly, an increased CD86+ population revealed increased maturation of dendritic cells, following the same pattern as Abseff group of the melanoma model." (PMID 36944686, 2023). "Mature DCs express a plethora of co-stimulatory markers, including CD80 and CD86 (cluster of differentiation 80 and 86, respectively), which are essential for activation of melanoma-specific T cells." (PMID 35248056, 2022). "CTLA4, an immunological checkpoint molecule, can influence the TME of CM by binding to B7 (CD80/CD86) molecules on melanoma antigen-presenting cells to down-regulate T cell activation." (PMID 35957907, 2022). "A contributing factor to the lack of optimal CD4+ T cell activation is the absence or low levels of the co-stimulatory molecules CD80 and CD86 on melanoma cells." (PMID 35162988, 2022). "Further, ABCB5+ melanoma CSCs preferentially inhibited IL-2–dependent T-cell activation in a CD86-dependent manner and induced CD4+CD25+FoxP3+ regulatory T cells (T-regs)." (PMID 33806296, 2021). "Specifically, treatment with INAPs-PTT increased the expression of co-stimulatory markers CD80 and CD86 on melanoma cells in vitro." (PMID 31963449, 2020). "The monocytes associated with melanoma are restrained in their expression of CD80 and CD86 co-stimulatory molecules but retain CD14 and HLA class II expression, thus finally promoting the expansion of CD11b+/Gr-1+ MDSCs." (PMID 29755693, 2018). "It upregulated major histocompatibility complex (MHC) and co-stimulators CD40 and CD86 expression, promoting melanoma cells’ antigen presenting capability." (PMID 30537988, 2018). "On the aspect of CD molecular expression, increased CD4 and CD86 were detected on the melanoma models treated with Tα1 and Tα1-Fc." (PMID 30120362, 2018).
melanoma (continued). "Inhibition of costimulation was confirmed by imaging flow cytometry whereby fluorescently labeled melanoma EVs colocalized with DCs and correlated with decreased CD86 expression compared to DCs matured in the presence of CD40L alone." (PMID 28424693, 2017). "In the B16.F10 melanoma model, CD86 surface expression was significantly up-regulated on cDCs in tumor draining lymph nodes in mice treated with anti-CD40 mAb in combination with sunitinib versus control." (PMID 27385210, 2016). "Altogether, our results suggest that HIFU down-regulates miR-134 to release the inhibition of miR-134 on CD86 in melanoma cells, thereby enhancing anti-tumor immune response." (PMID 26485753, 2015). "Supernatants (SNs) of melanoma cells whose cell death was modulated with zVAD-fmk induced an upregulation of the activation markers CD86 and MHCII on macrophages." (PMID 25973681, 2015). "The results suggest that HIFU down-regulates miR-134 to release the inhibition of miR-134 on CD86 in melanoma cells, thereby enhancing anti-tumor immune response." (PMID 26485753, 2015). "Taken together, these results imply that HIFU suppresses the expression of miR-134 in melanoma cells to enhance CD86 expression, which enhances anti-tumor immunity by triggering IFN-γ and TNF-α secretion from lymphocytes." (PMID 26485753, 2015). "The polarization towards regulatory T cells by ABCB5+ melanoma initiating cells has been attributed in part to the expression of co-stimulatory CD86 by these cells." (PMID 21526207, 2011). "Then the corresponding results from immunofluorescence assay has suggested that the knockdown of EBI3 in melanoma cells contributed to the reduced CD206 fluorescence intensity yet the increased CD86 fluorescence intensity in these induced macrophages from THP-1 monocytes (p-value < 0.05)." (PMID 39726752, 2024). "Moreover, there is a strongly positive correlation between the expression of IFNG and CD86 in melanoma tissues." (PMID 38491004, 2024). "It is possible to speculate that overexpression of antigen presentation molecules (e.g. MHC-I and II) and co-stimulatory molecules (e.g. CD80 and CD86) can enhance anti-tumour immune response in the melanoma model." (PMID 38668817, 2024). "In vivo, the development of a CD86‐P2A‐EGR3 recombinant mRNA vaccine not only triggers melanoma cells to undergo Schwann cell‐like differentiation but also augments immune infiltration via the NK‐cDCs‐CD8+T‐cell axis, ultimately resulting in effective tumor control." (PMID 38973154, 2024). "However, IRF7 knockdown with small interfering RNA (siRNA) significantly inhibited these inflammatory factors (IL‐1β, TNF‐α, IFN‐α, and IFN‐β), CD80 and CD86 in macrophages co‐cultured with irradiated melanoma cells." (PMID 38286661, 2024). "Furthermore, these trained DCs exhibited higher CD86 expression, and the CTB-trained mice displayed an effective antitumor immunity against melanoma challenge, associated with a robust infiltration of highly co-stimulatory DCs and functional CD8 T cells." (PMID 38812523, 2024). "Therefore, we further designed a recombinant CD86‐P2A‐EGR3 mRNA vaccine to induce melanoma cell Schwann cell‐like differentiation and enhance immune response." (PMID 38973154, 2024). "Furthermore, analysis of the change in the expression of immune scMEP markers from iDC to mDC, revealed significant downregulation of CD86 and HLA-DR in melanoma patients with a progressive decrease in worse outcome group DC." (PMID 37938561, 2023). "Interestingly, GILT expression in melanoma lines resulted in elevated CD86 protein levels detected by western blot analysis, consistent with the immunofluorescence analysis of the J3.DR4.GILT tumor." (PMID 35162988, 2022). "Previously, we have reported that the in vitro stimulation with the melanoma cell lysate TRIMEL to primary human AM cells mediated up to four-fold induction of several surface markers associated with DCs maturation such as MHC-I, MHC-II, CD80, CD83, and CD86." (PMID 35805888, 2022).
melanoma (continued). "Therefore, we examined the correlation between IL-32 gene expression and the DC marker CD11c (also known as ITGAX) as well as the costimulatory molecules CD40, CD80, and CD86 in melanoma samples from The Cancer Genome Atlas (TCGA)." (PMID 32841222, 2020). "Indeed, an elevated expression of CD40 and CD86 was observed in THP-1 cells exposed to melanoma-derived sEVs." (PMID 31269655, 2019). "We investigated whether the use of a MART-1 expressing chimeric Ad5/3, targeting CD80 and CD86 on DCs, could result in efficient priming and activation of melanoma specific CD8+ T effector cells both in vitro and in a human ex vivo SLN model." (PMID 30022005, 2018). "Interestingly, expression of costimulatory markers CD83 and CD86 were significantly decreased in DCs treated with melanoma-derived EVs compared to either liposome-treated DCs or DCs alone." (PMID 28424693, 2017). "As a positive co-stimulatory molecule, CD86 expressed on the melanoma cell membrane may provide a second signal for T cell activation, which enhances anti-tumor immune response." (PMID 26485753, 2015). "Interestingly, ex vivo-differentiated B16-MDSCs were phenotypically equivalent to in vivo B16 melanoma intra-tumor MDSCs on representative markers, which included CD86, MHC II, CD62L, arginase-1 and PD-L1." (PMID 25151659, 2014). "In melanoma, NK cells could significantly increase the expression of CD86, and ligation of CD86 with CTLA4Ig significantly increased the ability of NK cells to kill tumor cells." (PMID 25299645, 2014). "We are currently testing a first generation K562 aAPC expressing CD64, CD86, and 4-1BBL for its ability to expand melanoma TIL and whether it enhances the expansion of CD8+ T cells with similar properties as those found here." (PMID 23560068, 2013). "Previously we reported that in vitro treatment with GGTI-298 induces a dose-dependent increase in the membrane expression of CD80 and CD86 costimulatory molecules in the murine melanoma cells B16F10 and an increase in CD86 in two human melanoma cell lines, including LB1319-MEL." (PMID 20140259, 2010). "Interestingly, training-induced by CTB promotes a highly co-stimulatory phenotype in tumor-infiltrating DCs (CD86+) and a heightened functionality of exhausted CD8 T cells (Ki67+, GZMB+), which were associated with a protective response against melanoma challenge in vivo." (PMID 38812523, 2024). "In addition, our results from trained mice show that InfDCs could protect mice against melanoma because these cells robustly infiltrated trained mice highly expressing CD86." (PMID 38812523, 2024). "Therefore, we aimed to determine the expression levels of CD80, CD86, and PD -L1 in malignant melanoma tissue samples by immunohistochemistry and to investigate the possible relationship between these proteins and the clinicopathological features in this study." (PMID 37614091, 2024). "We have previously reported that the addition of the heat shock-conditioned melanoma lysate TRIMEL to IL-4/GM-CSF-activated monocytes (AM) mediates the induction of canonical surface markers associated with DC maturation such as MHC I, MHC II, CD80, CD83, and CD86." (PMID 31886313, 2019). "Amazingly, a single miRNA could affect numerous of target genes coincidently, for instance, it has been reported that miR-134 suppresses progression of melanoma by down-regulating CD86; and miR-134 could modulate resistance to doxorubicin in human breast cancer cells by repressing ABCC1 oncogene." (PMID 27166267, 2016). "We previously demonstrated that murine B16F10 melanoma cells present a modified phenotype following in vitro treatment by mIFN-γ in association with GGTI-298, characterized by an up regulation of MHC-I and the GGTI-induced expression of CD80 and CD86 costimulatory molecules." (PMID 20140259, 2010). "Mortality was lower in superficial spreading melanoma and Lentigo maligna melanoma types, whereas staining positivity of CD80 and CD86 was higher." (PMID 37614091, 2024).